SALL4 (spalt like transcription factor 4)
Diseases named in the same sentence as SALL4 in open-access papers (continued):
Sharing a sentence is not in itself a finding about the gene and the disease.
lymph node metastasis (9 papers, 2013 to 2025). "Our findings are consistent with those of previous reports, which indicated that SALL4 levels were positively associated with lymph node metastasis and that SALL4 is an indicator of metastatic potential in GC." (PMID 33644042, 2021). "The relationship between lymph node metastasis, histological grading, clinical staging, and the expression of SALL4 in carcinoma tissues was analyzed." (PMID 35692499, 2022). "This study suggested that the function of SALL4 in promoting lymph node metastasis and the advanced clinical stage is partly due to its interaction with β-catenin." (PMID 34944911, 2021). "Particularly, 35 (92.1 %) of 38 ESCC patients with lymph node metastasis showed high level of SALL4 expression." (PMID 27329034, 2016). "Our results reveal that SALL4 expression was strongly correlated with lymph node metastasis and advanced clinical stage." (PMID 27329034, 2016). "The frequency of lymph node metastasis was significantly higher in SALL4-positive cases than in SALL4-negative cases (P = 0.0460)." (PMID 26317546, 2015). "Of nine patients with lymph node metastasis, all (100%) overexpressed SALL4 (mean ± SD: 6.45 ± 1.38), while in 15.2% of patients (5 of 33) without metastasis to lymph nodes SALL4 was not overexpressed (mean ± SD: 4.68 ± 3.72)." (PMID 23363002, 2013). "Our data shows SALL4 overexpression in significant correlation with lymph node metastasis and epithelial-mesenchymal transition (EMT)." (PMID 23363002, 2013). "Moreover, SALL4 and β-catenin colocalized and interacted with each other in promoting lymph node metastasis and an advanced clinical stage." (PMID 35216168, 2022). "However, as in previous studies, SALL4 expression positively correlated with lymph node metastasis, tumor node metastasis, and Dukes’ stages." (PMID 34944911, 2021). "Univariate Cox regression analysis revealed that the TNM stage, Lauren type, degree of differentiation, SALL4 expression, lymph node metastasis, vascular invasion, perineural invasion, location, sex, and distant metastasis were the significant prognostic indicators of GC (P < 0.05, respectively)." (PMID 33644042, 2021). "SALL4 expression in CRC tissue and serum correlates with the degree of lymph node metastasis (LNM), differentiation degree, and staging, and patients with high SALL4 expression usually have a shorter mean survival time than those with low SALL4 expression." (PMID 38584262, 2024). "According to previous reports, SALL4 is high-expressed in the serum and tissues of COAD, and its expression level in serum and tissues is closely related to lymph node metastasis, differentiation degree, and Dukes staging." (PMID 35692499, 2022). "Furthermore, SALL4-positive patients exhibit an enhanced propensity for metastasis, and CEA-positive correlated with a higher lymph node metastasis rate." (PMID 39928247, 2025). "Meanwhile, our immunohistochemistry results supported that patients with lymph node metastasis and advanced tumor stages had a stronger expression of SALL4 compared to those without lymph node metastasis and with early tumor stages." (PMID 27329034, 2016).
gastric adenocarcinoma (8 papers, 2021 to 2025). "In gastrointestinal cancers, diagnostic biomarkers such as SALL4 and Glypican 3 are used to identify "gastric adenocarcinoma or CRAC with enteroblastic differentiation (GAED or CRAED)," but JIAED has not been reported previously." (PMID 40403397, 2025). "SALL4 is overexpressed in gastric adenocarcinoma and positively correlated with tumor progression and poor prognosis." (PMID 39703839, 2024). "Analyses of clinical specimens via TCGA datasets were performed to determine the expression level and clinical significance of SALL4 in STAD (Stomach Adenocarcinoma)." (PMID 37525212, 2023). "Both the serum AFP level and immunohistochemical expression of AFP/GPC3/SALL4 can be used to indicate a poor prognosis for gastric adenocarcinoma." (PMID 34706681, 2021). "Histopathological examination revealed that the type 3 lesion contained cells with pale sporangia, and immunohistochemistry was positive for SALL4, α-fetoprotein, and Glypican-3, leading to a diagnosis of gastric adenocarcinoma with enteroblastic differentiation (GACED)." (PMID 41041100, 2025). "In this study, we collected gastric adenocarcinoma cases with definite sAFP levels and then analyzed their clinicopathological characteristics and immunohistochemical results of AFP, GPC3, and SALL4." (PMID 34706681, 2021).
ovarian carcinoma (8 papers, 2016 to 2025). A malignant neoplasm originating from the surface ovarian epithelium. "SALL4 in ovarian cancer most often co-occurs with other tumor markers, especially in germ cell and serous tumors, and this co-expression has significant prognostic and diagnostic value." (PMID 41373846, 2025). "Previous clinical research in ovarian cancer patients indicated overexpression of SALL4 protein while conflicting expression patterns for ALDH1A1 at the protein level have been reported in ovarian cancer studies." (PMID 35090523, 2022). "SALL4 is a marker of poor prognosis in serous ovarian cancer, which can promote the invasion and metastasis of ovarian cancer cells." (PMID 36110943, 2022). "SALL4 is a tumor marker that most often co-occurs with other markers in ovarian cancer, although in some cases, it may be present on its own." (PMID 41373846, 2025). "However, in preliminary studies, positive association of SALL4 and ALDH1A1 expression proteins were reported separately with advanced FIGO stage in ovarian cancer tissue samples." (PMID 35090523, 2022). "SALL4 is a cancer marker that is abnormally expressed in ovarian cancer." (PMID 34512161, 2021). "High levels of SALL4/ALDH1A1 co-expression are an independent prognostic factor for poor progression-free survival and disease-specific survival, making this co-expression a potential biomarker for ovarian cancer progression." (PMID 41373846, 2025). "Earlier investigations on ovarian cancer have focused on the analysis and characterization of the expression of these two markers, separately while there are no studies of the combinations of SALL4 and ALDH1 in ovarian cancer." (PMID 35090523, 2022). "Parallel to the well characterized interaction between the Let-7 microRNA family and SALL4 during development, several recent studies demonstrate that Let-7/miR-98 may act as a tumor suppressor via targeting SALL4 in HCC, non-small cell lung cancer (NSCLC), and ovarian carcinoma." (PMID 34573282, 2021).
non-small cell lung carcinoma (6 papers, 2014 to 2024). A group of at least three distinct histological types of lung cancer, including non-small cell squamous cell carcinoma, adenocarcinoma, and large cell carcinoma. "Recent studies have shown that SALL4 is involved in leukemogenesis and a marker for hepatoblastoma and non-small cell lung carcinoma." (PMID 29625565, 2018). "Furthermore, SALL4 was recently identified as a novel marker for hepatoblastoma, non-small cell lung carcinoma, and gastric cancinoma." (PMID 29625565, 2018). "Among non-small cell lung cancers (NSCLCs), 16.2% were positive for SALL4 expression." (PMID 27705911, 2016). "In this study, we evaluated the expression of SALL4 and OCT4 in non-small cell lung carcinomas (NSCLC) by immunochemistry." (PMID 25346886, 2014). "In addition, this tumor frequently displays the robust expression of one or more stem cell markers, such as SOX2, CD34, and SALL4, which can facilitate the differential diagnosis of SMARCA4-deficient non-small cell lung cancer (NSCLC) (SMARCA4-dNSCLC), typically negative for these markers." (PMID 38881888, 2024).
prostate carcinoma (6 papers, 2017 to 2024). A carcinoma that arises from epithelial cells of the prostate gland. "Furthermore, SALL4 is involved in invasion of different tissues by various epithelial cancers, such as colon villous epithelial cancer and prostate cancer." (PMID 29228922, 2017). "We find that MBNL1-AS1 has been reported to inhibit the progression of prostate cancer by sponging miR-181a-5p and regulating PTEN/PI3K/AKT/mTOR signaling and PTEN signaling happens to be regulated by PLK1, PAF, YB-1, TWIST, YY1, KLF4, and SALL4." (PMID 35518784, 2022). "Additionally, the amplification percentages of SALL4 (27%) and FGF2 (10%) were determined when the seven-gene signature was analyzed for prostate cancer type, indicating that co-expression genes of OCT4 partially regulates cancer development." (PMID 30287838, 2018).
esophageal cancer (5 papers, 2017 to 2024). A primary or metastatic malignant neoplasm involving the esophagus. "Nicotine promotes the stabilization and expression of SALL4 by upregulating the RNA-binding protein interleukin enhancer binding factor 2 (ILF2), which facilitates tumor initiation in esophageal cancer cells." (PMID 38584262, 2024).
gastric tumor (5 papers, 2021 to 2025). "In light of the ongoing ambiguity surrounding SALL4's role in cancer, our study specifically aimed to elucidate the expression and significance of the SALL4-A isoform in gastric tumors." (PMID 39905414, 2025). "Our study specifically focused on isoform "A" of SALL4, which demonstrated elevated cytoplasmic expression correlated with better prognosis of gastric tumor cells." (PMID 39905414, 2025). "Rare hepatoid carcinomas can also be suspected in the context of a primary gastric tumour showing an adenocarcinomatous component with positive Sal-like protein 4 (SALL4) immunostaining." (PMID 36159217, 2022). "A significant correlation was found between SALL4 mRNA expression and H. pylori infection in which 50% (43/86) and 40.7% (35/86) gastric tumor samples were positive for 16s rRNA/UreC (p = 0.047) and CagA (p = 0.036), respectively." (PMID 33745265, 2021). "Although there is broad acknowledgment that the SALL4 transcription factor predominantly localizes within the cell nucleus, our examination revealed a distinctive pattern of SALL4-A translocation in gastric tumors." (PMID 39905414, 2025). "Consequently, assessing the effects of each isoform is crucial for unraveling the roles of SALL4 in gastric tumor behavior." (PMID 39905414, 2025). "SALL4 mRNA expression was significantly increased in primary gastric tumors when compared with adjacent non-tumor tissues (P < 0.001)." (PMID 33644042, 2021).
hepatoblastoma (5 papers, 2014 to 2023). Hepatoblastoma (HB) is a malignant hepatic tumor and is the most common pediatric liver cancer. "Hepatoblastomas with high expression levels of stem/progenitor cell markers (EpCAM, LIN28B, SALL4, HMGA2, AFP) are usually associated with poor prognosis." (PMID 37414763, 2023). "Extramedullary haematopoiesis and hepatoblastoma-like morphology, which were each observed in one SALL4-positive HCC, were noteworthy in this context." (PMID 26034695, 2014).
hepatoid adenocarcinoma (5 papers, 2015 to 2026). An adenocarcinoma with morphologic characteristics similar to hepatocellular carcinoma, arising from an anatomic site other than the liver. "A combination of palate, lung, and nasal epithelium carcinoma-associated protein (PLUNC), hepatocyte paraffin 1, and SALL4 were reliable prognostic indicators in hepatoid adenocarcinoma of the stomach." (PMID 26317546, 2015). "Therefore, SALL4 can serve as a specific and effective marker for differentiating hepatoid adenocarcinoma from HCC." (PMID 37950062, 2023). "In a previous study of hepatoid adenocarcinomas, AFP was positive in 80% cases, SALL4 was positive in 47%, HepPar‐1 was positive in 69%, and GPC3 was positive in 56%." (PMID 41190289, 2026). "Furthermore, immunohistochemically, hepatoid adenocarcinoma shows positive expression of SALL4, whereas HCC exhibits negative expression." (PMID 37950062, 2023).
intrahepatic cholangiocarcinoma (5 papers, 2015 to 2022). A carcinoma that arises from the intrahepatic bile duct epithelium in any site of the intrahepatic biliary tree. "Downregulation of SALL4 contributed to a decrease in B-cell-specific Moloney murine leukemia virus integration site 1 (Bmi-1) expression and inactivated the Wnt3a/β-catenin signaling pathway in intrahepatic cholangiocarcinoma (ICC)." (PMID 35216168, 2022).
lymphoma (5 papers, 2012 to 2024). A malignant (clonal) proliferation of B- lymphocytes or T- lymphocytes which involves the lymph nodes, bone marrow and/or extranodal sites. "Differential diagnosis was performed via immunohistochemistry (IHC), showing a loss of BRG1 and claudin-4, SALL4 expression, CD34, SMARCAB1, and negative lymphoma markers." (PMID 38542211, 2024).
serous ovarian cancer (5 papers, 2022 to 2025). "One immunohistochemistry study has also validated the high expression of SALL4 in SCCOHT compared to high-grade serous ovarian cancer." (PMID 39906560, 2025). "Bioinformatics analysis has shown an interaction between the SALL4 and ALDH1A1 genes, and high coexpression of SALL4/ALDH1A1 in serous ovarian carcinoma is significantly associated with distant metastasis and aggressive tumor behavior." (PMID 38584262, 2024). "In serous ovarian cancer (SOC), SALL4 has been shown to be frequently co-expressed with the ALDH1A1 marker, and high co-expression of these two proteins is significantly associated with advanced disease stage, metastasis and poorer prognosis." (PMID 41373846, 2025).
trophoblastic tumors (5 papers, 2017 to 2024). "Expression has been also reported SALL4 does not seem to be expressed in all trophoblastic tumors, individual genetic difference may be responsible for this phenomenon based on our relatively small sample, the more samples the more valuable outcome can be obtain." (PMID 28887597, 2017).
breast tumor (4 papers, 2019 to 2023). "In some cases, activation correlates with co-occupancy of regulatory sites by RING1B and transcription factors critical for cell lineage identity, for example Spalt Like Transcription Factor 4 (SALL4) in spermatogonia or Estrogen receptor alpha in breast tumor cells." (PMID 34968234, 2019). "In the SQ breast tumors, we observed significantly upregulated mRNA levels of the Oct3/4 regulatory network, including ONSS, and several other PTFs, including Nanog, Sall4, Sox2, Sox4, FoxA2, Gata6, Zic2 and HoxB7, as well as Oct3/4 isoform B, polycomb suppressors Bmi1, EzH2, Amigo and Dkk1." (PMID 37298091, 2023). "Regardless of tumor type, Nodal and SALL4 were detected in all breast tumor tissues." (PMID 34476264, 2021).
clear cell renal cell carcinoma (4 papers, 2020 to 2023). "Additionally, VHL mutation-mediated SALL4 overexpression promoted clear cell renal cell carcinoma (ccRCC) cell proliferation, colony formation, cell cycle progression, migration, invasion, tumorigenicity, and tumor vascularization through modulating Akt/GSK-3β axis and VEGF-A expression." (PMID 37525212, 2023).
Duane retraction syndrome (4 papers, 2011 to 2023). Duane retraction syndrome (DRS) is a congenital form of strabismus characterized by horizontal eye movement limitation, globe retraction and palpebral fissure narrowing in attempted adduction. "Although most cases do not have an identifiable genetic cause, autosomal dominant variants in CHN1 or MAFB can cause isolated Duane syndrome, and variants in SALL4 cause Duane-radial ray syndrome (Duane syndrome plus abnormalities of forearm development)." (PMID 38500555, 2023).
glioblastoma (4 papers, 2018 to 2022). The most malignant astrocytic tumor (WHO grade IV). "The associations of SALL4 with these three microRNAs were analyzed in 43 glioblastoma patients with Spearman’s correlation analysis." (PMID 30423818, 2018). "Cells expressing proteins including SOX2, OCT4, pSTAT3, KLF4, NANOG, and SALL4 were identified as CSCs in Glioblastoma multiforme (GBM)." (PMID 33799834, 2021).
multiple myeloma (4 papers, 2022 to 2025). "IMiDs are known to induce degradation of zinc-finger transcription factors in myeloma cells, like IKZF1 and IKZF3, and like SALL4 in embryonic stem cells, which is behind their therapeutic, but also teratogenic functions." (PMID 39972349, 2025).
myeloid leukemia (4 papers, 2009 to 2021). A clonal proliferation of myeloid cells and their precursors in the bone marrow, peripheral blood, and spleen. "The expression pattern appeared different for SALL4 in the different myeloid leukemia in comparison with the HI group (median: 0.394)." (PMID 23067006, 2012). "SALL4 expression was strongly correlated with BMI-1 in most of the myeloid leukemia patient groups, providing a potential link between SALL4 and BMI-1 in leukemogenesis." (PMID 23067006, 2012). "The in vivo repressive effect(s) of SALL4 were evaluated in SALL4 transgenic mice, where decreased expressions of PTEN and SALL1 were associated with myeloid leukemia and cystic kidneys, respectively." (PMID 19440552, 2009). "Further studies will be needed to determine whether BMI-1 and SALL4 are novel therapeutic targets for leukemic stem/initiation cells in primary myeloid leukemia." (PMID 23067006, 2012). "In order to characterize the expression pattern of SALL4, BMI-1 and ABCA3 genes in patients with myeloid leukemia and those who achieved complete remission (CR) after chemotherapy." (PMID 23067006, 2012). "The BMI-1 and SALL4 genes were detected in all of the PBMC samples from the healthy individuals and those with myeloid leukemia." (PMID 23067006, 2012). "Little is known about the expression pattern of the SALL4, ABCA3 and BMI-1 genes in patients with myeloid leukemia and patients that achieved complete remission after chemotherapy." (PMID 23067006, 2012). "Sal-like protein 4 (SALL4) and B cell-specific MLV integration site 1 (BMI-1) are important factors in hematopoiesis and are expressed in hematopoietic stem/progenitor cells (HSCs/HPCs) and myeloid leukemia cells." (PMID 23632167, 2013).
nasopharyngeal carcinoma (4 papers, 2019 to 2024). A carcinoma arising from the nasopharyngeal epithelium.
ovarian tumors (4 papers, 2012 to 2024). "This study evaluates the expression of SALL4 and OCT3/4 biomarkers in pediatric ovarian tumors and their associations with tumor subtype, stage, and clinical outcome." (PMID 38928458, 2024). "In summary, SALL4 was expressed in a subset of MMMTs with a higher frequency than that of other ovarian tumors." (PMID 22848863, 2012).
squamous cell carcinoma (4 papers, 2016 to 2023). A carcinoma arising from squamous epithelial cells. "Within the NSCLC cases, SALL4 was found to be positive in 12% of adenocarcinomas (ADC) (n=100), 19% of adenocarcinoma in situ (n=21) and 23% of squamous cell carcinoma (SCC) (n=52)." (PMID 27705911, 2016).
anal stenosis (3 papers, 2018 to 2024). "Mice with heterozygous deletion of Sall4 show a high frequency of miscarriage, while surviving litters show ventricular septal defects and anal stenosis, both phenotypes that are observed in humans with DRRS or thalidomide syndrome." (PMID 30067223, 2018). "Moreover, Sall4+/−; Sall1+/− mice exhibit renal agenesis and anal stenosis, demonstrating genetic interactions between Sall genes." (PMID 38345319, 2024).
carcinosarcoma (3 papers, 2023 to 2025). A malignant tumor composed of a mixture of carcinomatous and sarcomatous elements. "Recently, immunohistochemical markers, including SALL4 and CD10, have been developed as distinguishable markers for carcinosarcoma." (PMID 40556673, 2025).
chronic myeloid leukemia (3 papers, 2017 to 2022). "SALL4 is expressed in 75% of chronic myeloid leukemia (CML) patients in blast-crisis, but expressed in just 10% of patients in the chronic phase." (PMID 36010677, 2022).